CDK4 (cyclin dependent kinase 4)
Diseases named in the same sentence as CDK4 in open-access papers (continued):
Sharing a sentence is not in itself a finding about the gene and the disease.
cancer (continued). "Knockdown of Gls1 increased the expression of Cdkn1a and Cdkn1b and decreased the expression of some critical oncogenes for cancer cell survival, such as c-Myc, Cdk4, and NfκB, as well as some genes which are essential for MM cell survival, such as Irf4, Prdm1, Csnk1α1, and Rassf5." (PMID 31666930, 2019). "Palbociclib (PD0332991) is an anti-CDK4/6 chemical for cancer treatment." (PMID 31652270, 2019). "Altogether, these results suggest that the choice of the drug delivery schedule may depend on the type of cancer and is therefore a critical aspect requiring careful consideration when planning CDK4/6 inhibitors plus chemotherapy-based therapies." (PMID 31506466, 2019). "More importantly, the gain-of-DEDD drives a previously unknown cancer-specific vulnerability to CDK4/6 targeting agents in combination with EGFR inhibitors, regardless of the Rb status of the TNBC cells." (PMID 31253784, 2019). "Also, studies demonstrated that cyclin D-CDK4 kinase destabilized PD-L1 via Cullin3SPOP to control cancer immune surveillance and revealed the potential combination of CDK4/6 inhibitors and PD-1/PD-L1 blockade to enhance therapeutic efficacy for human cancers." (PMID 31777590, 2019). "CDK4 is crucial for various oncogenic transformation processes suggesting that many cancer cells may be addicted to high CDK4 activity." (PMID 29451912, 2018). "Moreover, CDK4/6 inhibition has been reported to synergize with MEK inhibition in a variety of cancers driven by mutant RAS, including NSCLC." (PMID 30167080, 2018). "Metformin has been shown to block cyclin D1, Cdk4 and Cdk6 in various cancers." (PMID 29765528, 2018). "In addition, a combinatorial drug screen on multiple PIK3CA mutant cancers with decreased sensitivity to PI3K inhibitors revealed that combined CDK4/6-PI3K inhibition synergistically reduces cell viability." (PMID 30518851, 2018). "Although the details of this regulatory event are not yet defined, it is tempting to speculate that this reflects context specific transformation events that sensitize cancer cells to CDK4/6 inhibitors." (PMID 29789718, 2018). "RB-E2F signaling pathway is often inactivated in cancer due to various reasons including RB1 loss, RB hyperphosphorylation through increased activity of CDK4/CDK6, or E2F hyperphosphorylation, all of which prevent repression of E2Fs from binding to downstream targets." (PMID 30220967, 2018). "While many cell cycle genes are indeed suitable cancer drug targets (e.g. CDK4 and CDK6), other genes may be up-regulated during normal cell division but dispensable for this process." (PMID 29417930, 2018). "As metabolic characteristics of cancer gradually evolve as a therapeutic target, the CDK4/6 inhibitor-mediated metabolic state might be considered as a therapeutic target." (PMID 30340359, 2018). "However, recent evidence supporting the preferential dependence of cancer cells on interphase CDKs, including CDK4 and CDK6, suggests higher efficiency of a new class of agents targeting CDKs." (PMID 29568361, 2018). "Despite the co-amplification of genes encoding CDK4 and MDM2 in human malignancies, our results indicate that targeting both simultaneously may be counterproductive for cancer therapy." (PMID 30206211, 2018). "However, there is additional need for optimisation of these treatment strategies since CDK4/6 inhibition antagonises chemotherapy and radiotherapy as their efficacy mostly relies on the fact that cancer cells undergo fast and uninhibited cell divisions." (PMID 30340359, 2018). "In contrast, due to the minimal G1T38 compound in the plasma at 24 hours, the bone marrow seem to have more time to recover from CDK4/6 inhibition between doses suggesting that continuous daily dosing may be achievable in cancer patients." (PMID 28418845, 2017).
cancer (continued). "Five-point-five percent 5.5% of these patients displayed somatic alterations classified as 2b, defined as an approved biomarker in another cancer indication and included ERBB2 amplifications, CDK4 amplifications, BRCA1/2 mutations, BRAFV600E mutation and fusion events involving ROS1 and ALK1." (PMID 29156578, 2017). "In addition to affecting growth and viability of cancer cells in 2D cultures, CDK4/6 knockdown reduced the anchorage‐independent growth of HCT116 cells." (PMID 28978620, 2017). "In sum, our metabolic and transcriptomic analyses have revealed that depletion or inhibition of CDK4/6 in cancer cells leads to de novo addiction to MYC, and, as likely downstream consequences, also to glutaminase and mTOR signaling, as well as to a compromised adaptation to hypoxia." (PMID 28978620, 2017). "We also investigated whether the upregulation of PI3K/Akt in response to CDK4/6 inhibition represented an additional cancer cell vulnerability." (PMID 28978620, 2017). "Mutual exclusivity analysis with genomic alteration data showed that STK11 alterations in cancer patients rarely co-occur with CDK4, CDKN2A, CDKN2B or RB1, supporting a role for STK11 in an oncogenic pathway that is intimately associated with cell cycle function." (PMID 28205554, 2017). "As both CDKN2C and RB1 interact with G1/S cell cycle checkpoint through CDK4/6, they are potentially targetable through CDK4/6 inhibition, for which it has been shown in other cancers that co-deletion of CDKN2C and CDKN2A with functional presence of RB1 increases sensitivity in cell lines." (PMID 28427158, 2017). "Our data further indicate that high level of CDK4 expression may contribute to poor prognosis features and poor clinical outcomes by increasing the cancer stem cell numbers." (PMID 27759034, 2016). "However CDK4/6 inhibitors are often ineffective in treating TNBC, likely due to loss of Rb in this cancer type." (PMID 27486754, 2016). "Thus, the CDK4 inhibition offers an attractive therapeutic strategy for anti-cancer development due to the importance of CDK4 activity in regulating cell proliferation." (PMID 27670681, 2016). "This study supports the hypothesis that PF exerts anti-cancer activity, and downregulation of cyclin D1 and CDK4 plays a role in PF-induced anti-cancer activity." (PMID 27670681, 2016). "Since CDK4 is the key regulator of the G1-S cell-cycle transition and drives cell-cycle progression, CDK4 inhibitors might offer new strategies for a targeted cancer therapy." (PMID 27662657, 2016). "To investigate the role of CDK4 in cancer stem cell expansion, and to further examine whether CDK4 could be used as a potential drug target for TNBC patients, we used the pharmacological CDK4 inhibitor, palbociclib." (PMID 27759034, 2016). "For example, cyclin D1, which enhances transcriptional regulation in several human cancers, promotes progression through the G1-S phase of the cell cycle by binding to CDK-4 to phosphorylate and inactivate retinoblastoma protein and release E2F transcription factors." (PMID 27811358, 2016). "Some inhibitors of the cyclin D-associated kinases CDK4 and CDK6 may be used as potential cancer therapeutics." (PMID 27230400, 2016). "In contrast, cancers that lack Rb function may be resistant to CDK4/CDK6 inhibition because the antitumor effect of CDK4/CDK6 inhibition is partly due to downstream Rb phosphorylation." (PMID 25914884, 2015). "Future studies should determine whether expression levels of FZR1 or its proteolytic targets such as SKP2 provide prognostic markers for the response of cancer cells to CDK4/6 inhibitor treatment." (PMID 25562820, 2015). "LY294002 (PI3K inhibitor) could inhibit cancer cell proliferation and induce G1 arrest, accompanied by reduced cyclin D1 and CDK4 levels." (PMID 26592552, 2015). "Furthermore, VEGFA-induced activation of mTor signaling cascades also promoted cancer cell growth through cyclinD1 and CDK4 activation." (PMID 26308848, 2015).
cancer (continued). "Ultimately, the insights provided in this work have distinct diagnostic implications and suggest the possibility that targeting MDM2 or ATRX by small molecule in a combination with CDK4 inhibitor might be promising for cancer therapy." (PMID 26697514, 2015). "Moreover, increasing evidence supports a role for cyclin D1 and CDK4 in the promotion of cancer cell proliferation, and they are more abundant in lung tumor tissue than normal lung tissue." (PMID 25971210, 2015). "Elevated Cdk1, Cdk2 and Cdk4 mRNA levels were detected in proliferating malignant tumors." (PMID 25900242, 2015). "The importance of CDK4/6 in cell cycle control makes it an interesting target for cancer treatment." (PMID 26649278, 2015). "The Cancer Genome Atlas (TCGA) project has shown that CDKN2A/p16-CDK4/6-RB pathway is altered in nearly 80 % of primary GBMs with the most frequent genetic alterations being CDKN2A gene deletion or mutation, CDK4 amplification, and RB1 mutation or deletion." (PMID 26146488, 2015). "Many of the 12q fusion genes produced chimeric proteins or disrupted cancer-associated genes such as RUNX2, CCND3, and LRP1, indicating that some of the fusions may contribute to cancer progression independently of MDM2/CDK4 co-amplification." (PMID 25300797, 2014). "Deregulation of Cdk4 and cyclin D1 is widespread in human cancer." (PMID 24606538, 2014). "It was previously reported that the selective targeting of CDK4/6 kinase activity may block the cell cycle and thus inhibit cancer growth." (PMID 24765199, 2014). "Cytotoxic drugs are commonly used to treat cancer; combining CDK4/6 inhibitors with cytotoxic drugs may increase their clinical effectiveness." (PMID 24919854, 2014). "To explain the biological mechanism of cell proliferation suppression by doxazosin concerning cell cycle changes, we observed both, an inhibition of cell cycle-regulatory proteins such as cyclin D1 and CDK4, and expression of p21 in doxazosin-treated carcinoma cells." (PMID 25568671, 2014). "Wnt pathway thus, regulates the cancer cells entry into the cell cycle through the production of cyclin D. Cyclin D complexes with cyclin-dependent kinase 4/6 (Cdk4/6), inactivates the tumor suppressor protein retinoblastoma (Rb), and promotes the entry of the cell from G0 to G1 phase of cell cycle." (PMID 23596569, 2013). "CDK4 has been shown to be absolutely crucial for various oncogenic transformation processes, suggesting that many cancer cells may be addicted to high CDK4 activity." (PMID 23336272, 2013). "CDK1, CDK4, and CDK6 have a diagnostic value in various cancers." (PMID 22333595, 2012). "Finally, deregulated expression and/or amplification of cyclin D and cdk4 genes have also been observed in many cancers." (PMID 22125623, 2011). "Possibly the apparent discordance between results from CDK4 knockout cancer models, and Cdk4 kinase inhibitor studies could stem from such critical kinase-independent activities of Cdk4." (PMID 21668989, 2011). "Deregulation of Cdk4 is widespread in human cancer, CDK4 gene knockout is highly protective against chemical and oncogene-mediated epithelial carcinogenesis, despite the continued presence of CDK2 and CDK6; and overexpresssion of Cdk4 promotes skin carcinogenesis." (PMID 21668989, 2011). "Based on the positive role of Sei1 on Cdk4/D and E2f1 activities, it is conceivable that Sei1 could have a role in cancer and/or pancreatic islet biology." (PMID 20090907, 2010). "We did not identify in our dataset any significant and valid association of the CDK4 IVS4-nt40 G→A genotype variant with either cancer or tumors/cancer against control subjects with no cancer and no tumors/cancer, respectively." (PMID 19327170, 2009). "With respect to S-phase events both mouse models and studies on cancer-derived cells revealed that accumulation of cyclin D1/CDK4 complexes triggers DNA re-replication and, thus, could be specifically targeted in cancer cells." (PMID 18509533, 2008).
cancer (continued). "In order to determine whether this was also the case in the A2780 cancer cell line, p27 was immunoblotted in total CDK4 and CDK2 complexes isolated by immunoprecipitation from untreated cells." (PMID 17088910, 2006). "Binding and recognition between p16INK4a and CDK4 or CDK6 proteins are mediated primarily by hydrogen-bond networks, with several of the residues that participate in these interactions being mutated in cancer." (PMID 14735200, 2004). "The most successful CDK inhibitors are the dual CDK4/6 inhibitors, which could specifically block the retinoblastoma protein pathway participating in the transition from the G1 to the S phase of the cell cycle, thereby preventing cancer cell progression." (PMID 40040723, 2025). "In addition, CDK4/6 inhibitors affect the lipid metabolism of cancer cells." (PMID 40563591, 2025). "Additionally, inhibiting the expression of CDK4 may result in a more effective anti-cancer effect in HCC both in vitro and in vivo, providing a new therapeutic target for HCC." (PMID 38231074, 2025). "However, few cancer types are sensitive to CDK4/6i’s when used as single agents." (PMID 40696167, 2025). "Taken together, these findings underscore the critical role of CDK4/6 in regulating cancer cell metabolism, highlighting how their inhibition may unveil metabolic vulnerabilities that can be therapeutically exploited to overcome resistance and improve patient outcomes." (PMID 41388212, 2025). "Furthermore, the pan CDK inhibitors and CDK4/6 inhibitors have also been associated with significant systemic toxicity in various human cancers, especially in hormone-responsive, HER-2 negative, and metastatic breast cancer." (PMID 41463161, 2025). "Notably, therapies like CDK4/6 inhibitors require particularly close monitoring, creating logistical and capacity challenges for medical oncologists, whose workloads are already stretched due to rising cancer incidence and treatment complexities." (PMID 40710212, 2025). "However, even beyond these possibilities, many existing therapies (CDK4/6i, antibody–drug conjugates, and so on) may benefit from signature-based biomarkers that incorporate a cancer’s potential for evolution." (PMID 40379787, 2025). "Cancer cell migration and invasion may be promoted by cytoplasmic CDK4-cyclin D16." (PMID 40764324, 2025). "As one illustration, a comprehensive multi-omics study of CDK4/6 inhibitor response in cancer cells revealed networks of downstream and off-target effects, suggesting additional nodes (beyond CDK4/6) that a polypharmacological drug might modulate to improve efficacy." (PMID 40725243, 2025). "Since cell division is intimately related to cellular metabolism, it is not unexpected that by causing cell cycle arrest, CDK4/6 inhibitors might change the metabolism of cancer cells." (PMID 40563591, 2025). "However, to the best of our knowledge, no systematic comparative study of the characteristics of DNA‐damaging agent‐induced and CDK4/6i‐induced senescent cancer cells, particularly in terms of the expression patterns of SASP and ligands that modulate the TME, has been conducted." (PMID 37854019, 2024). "Additionally, Cyclin D1/CDK4-Rb pathway regulates the metastatic capacity of cancer cells." (PMID 39161904, 2024). "Therefore, our results do not exclude the possibility that the reduced estrogen levels following AI treatment could influence the process of TIS by CDK4/6i in the cancer tissue of patients." (PMID 37854019, 2024).
cancer (continued). "There may also be a bias created by the fact that 12% of the patients who received 1st-line therapy appeared to respond to ET for more than 5 years, which may indicate that the cohort of patients who received 2nd-line ET + CDK4/6i had more aggressive cancer and, therefore, worse outcomes." (PMID 38922546, 2024). "However, with data suggesting that mechanisms of resistance to CDK4/6 inhibitors seem uniform between the different agents, the higher odds of non-cancer deaths with abemaciclib relative to placebo compared to other CDK4/6 inhibitors is an important observation." (PMID 38326452, 2024). "Somatic copy number deletion of the CDKN2A gene is a transformed cell-specific event, which prompted scientists to study whether disruption of the CDKN2A deletion-related feedback regulatory loop may overcome the resistance of P16-inactivated cancer cells to CDK4 inhibitors." (PMID 39351198, 2024). "RB1 is frequently mutated in a number of cancers (7% in total, according to TCGA database), including sarcoma, bladder, endometrial, ovarian, breast, prostate and non-small cell lung (NSCLC) cancers, and the Rb protein is inactivated by high CDK4/6 or CDK2 activity." (PMID 38279263, 2024). "Thus, targeting this pathway could inhibit tumor growth and progression, suggesting that therapies combining CDK4/6 inhibitors with agents that modulate SMURF2 activity could enhance anti-cancer efficacy." (PMID 39697237, 2024). "Besides, four sex-biased exon skipping events in cancer therapeutic target genes (FDPS, FGFR1, CDK4, and IMPDH2) could cause the loss of partial protein function, which may contribute to a differential drug response rate in male and female patients." (PMID 39175079, 2024). "Our data indicate that upregulated mitogenic signaling in cancer may cause more effective adaptation to CDK4/6i than non-transformed cells." (PMID 38030655, 2023). "However, some cancers show resistance to CDK4/6i and have a poor prognosis." (PMID 37486454, 2023). "Therefore, it should be noted that some populations have cancers resistant to CDK4/6is." (PMID 37486454, 2023). "Furthermore, for patients showing cancer progression on CDK4/6i combined with AI, fulvestrant plus vinorelbine may also be a second-line option." (PMID 37144559, 2023). "Interestingly, P-Tex cells expressed CDK4 genes as high as cancer cells, which could be simultaneously inhibited by CDK4 inhibitors and might be a potential reason for the ineffectiveness of CDK4 inhibitors in treating HPV-positive HNSCC." (PMID 36811599, 2023). "Because ATM and CHK2 inhibitors are largely ineffective in cancer clinical trials, development of activators of these kinases might afford more complete cell cycle control especially in conjunction with cyclin-dependent kinase 4/6 (CDK4/6) inhibitors that have shown efficacy in the clinic." (PMID 37390209, 2023). "However, our studies showed that only inactivation of STING but not MAVS, could reverse the higher levels of ISG expression in Cdk4−/− and Cdk6−/− cancer cells." (PMID 37833461, 2023). "CDK4 and 6 phosphorylate the retinoblastoma protein (Rb), which is a major determinant of sustained cell proliferation in cancer, such as in the case of osimertinib-resistant cancer cells independent of the underlying mechanisms." (PMID 36765799, 2023). "Therefore, CDK4 inhibitors, which are already under clinical trials, could be used in combination therapy to prevent the cancer cells from escaping cell death if resistance occurs." (PMID 37174677, 2023). "Because of our novel finding that cyclin D1 promotes pyrimidine synthesis, we wondered whether combined inhibition of its main kinase partner (Cdk4) along with the downstream pyrimidine synthesis enzyme dihydroorotate dehydrogenase (DHODH) would synergistically block cancer cell growth." (PMID 38152849, 2023).